IGF1 (insulin like growth factor 1)
Diseases named in the same sentence as IGF1 in open-access papers (continued):
Sharing a sentence is not in itself a finding about the gene and the disease.
periodontitis (11 papers, 2012 to 2026). An acute or chronic inflammatory process that affects the tissues that surround and support the teeth. "Altogether, the findings presented in this study highlights that lncRNA MEG3 was determined as a biomarker as periodontitis inhibitor because of the new-found mechanism underlying lncRNA MEG3/miR-27a-3p/IGF1 axis via PI3K/Akt signaling pathway by promoting osteogenic differentiation in PDLSCs." (PMID 31398715, 2019). "Considering the fact that IGFBP-5 seems to be the only IGFBP tested in animal models of periodontitis, it would be a promising candidate for future clinical trials in addition to IGF-1 and IGF-2." (PMID 34940355, 2021). "For instance, IGF-1 combined with PDGF was applied to roots surfaces of teeth with periodontitis in beagle dogs following OFD." (PMID 34940355, 2021). "To conclude, lncRNA MEG3 sponged miR-27a-3p to up-regulate IGF1 to activate PI3k/Akt signaling pathway to promote PDLSC osteogenic differentiation in periodontitis." (PMID 31398715, 2019). "Similar to the expression of lncRNA MEG3, IGF1 expression was lower in periodontitis periodontal tissues, compared with healthy periodontal tissues." (PMID 31398715, 2019). "Taken together, IGF1 down-regulated in PI3K/Akt signaling pathway could be inactivated in periodontitis periodontal tissues compared with healthy periodontal tissues." (PMID 31398715, 2019). "Moreover, our result showed that lncRNA MEG3/miR-27a-3p/IGF1 axis definitely played a significant role in understanding the pathogenesis of periodontitis for better prognosis." (PMID 31398715, 2019). "However, because of the limitation of the samples we researched in this study, further confirmation should be needed in prospective researches of the pathological and physiological mechanism according to lncRNA MEG3/miR-27a-3p/IGF1 axis in periodontitis PDLSCs." (PMID 31398715, 2019). "Interestingly, hypoxia attenuated this upregulation, suggesting that IGF-1 may not be upregulated by occlusal forces in hypoxic deep periodontal pockets which may contribute to progression of periodontitis." (PMID 34940355, 2021).
pituitary deficiencies (11 papers, 2010 to 2025). "For this reason, GH deficiency was diagnosed according to IGF-1 levels, and it was assumed in the concomitant presence of at least three other pituitary deficiencies, in accordance with current guidelines." (PMID 37101307, 2023). "Meanwhile, we found that patients with lower IGF-1 had more severe injury reflected by pituitary deficiency, structural brain abnormality, and more contusions." (PMID 36062186, 2022). "Compared with patients with normal IGF-1, those with elevated IGF-1 and reduced IGF-1 were more likely to have a higher BMI, UA, TG, FBG, number of pituitary deficiencies, and lower HDL-C." (PMID 38370349, 2024). "When additional covariates, including cranial radiotherapy exposure and the number of pituitary deficiencies, were considered, the negative association between IGF-1 SDS and RHI persisted, although the overall model lost statistical robustness." (PMID 41374948, 2025).
rectal cancer (11 papers, 2005 to 2024). A primary or metastatic malignant neoplasm that affects the rectum. "Moreover, high serum levels of GH and IGF-1 enhance the proliferation rate of epithelial cells of the sigma crypts, which, by increasing the length of colon and sigma, would predispose to the development of colon-rectal cancer." (PMID 25962899, 2015). "The tumor suppressive ability of miR-195 in rectal cancer cell proliferation and metastasis was mediated by blocking IGF1 expression and inhibiting the PI3K/Akt pathway." (PMID 32984321, 2020). "Studies have found higher expressions of several components of the IGF system (including IGF-1, IGF-2, and IGF-1R) in normal rectal mucosa compared with colonic mucosa, which probably suggests a more pronounced tumor-promoting effect of the IGF system in rectal cancer." (PMID 35296101, 2022).
renal cell carcinoma (11 papers, 2002 to 2023). "Elevated IGF-1 signaling in renal cell carcinoma (RCC) patients is associated with poor prognosis, and correlates with the potency of tumor development and progression." (PMID 28978182, 2017). "Previous studies have demonstrated that IGF-1 pathway plays an important role in cell proliferation and apoptosis resistance in renal cell carcinoma." (PMID 37346909, 2023). "High IGF1/IGFBP3 ratio at diagnosis shows better prognosis in renal cell carcinoma." (PMID 37088808, 2023). "Insulin-like growth factor 1 (IGF1) and IGF binding protein 3 (IGFBP3) play an important role in the development and progression of renal cell carcinoma (RCC)." (PMID 27976731, 2016). "However, in their study, high serum IGF-1 levels at the time of diagnosis correlated with favourable prognosis; therefore, it seems that serum IGF-1 level may be an independent prognostic factor of renal cell carcinoma." (PMID 33008076, 2020).
rickets (11 papers, 2010 to 2023). Bone softening and weakening usually caused by deficiency or impaired metabolism of vitamin D. Deficiency of calcium, magnesium, or phosphorus may also cause rickets. "Our results suggest that among participants with higher GS (associated with elevated circulating IGF1), those who exhibit lower levels of vitamin D (hypovitaminosis D) exhibit higher BMI percentiles." (PMID 37892272, 2023). "The potential significance of this process involving IGF-1 was illustrated in a recent investigation of children with vitamin D-deficient rickets, before and after supplementation with vitamin D." (PMID 19807897, 2010). "Moreover, different authors have described, in patients diagnosed with nutritional rickets, how treatment with vitamin D involves an increase in IGF-1 levels with positive effects on length grow." (PMID 35626902, 2022). "For example, serum 25(OH)D3 was positively correlated with serum IGF-1 (r = 0.33) in healthy adults, and oral supplementation of a single dose of 300,000 IU vitamin D increased levels of IGF-1 and IGFBP-3 in children with rickets." (PMID 28417914, 2017). "Numerous studies have hypothesized an interaction between vitamin D and the GH/IGF-1 axis not just for patients affected by rickets." (PMID 30885216, 2019).
alcohol (10 papers, 2009 to 2025). "Our data pertaining to BDNF and IGF-1 support growth factors could be linked to alcohol dependence." (PMID 29108028, 2017). "Although the central mechanisms linking insulin/IGF-1 signaling to alcohol dependence remain unclear, we speculate that the long-term consequence of alcohol consumption suppresses these systems which may contribute to changes in cognitive behavior." (PMID 41400881, 2025). "Chronic alcohol reduced IL Igf1r and CA1 Igf1 transcript levels in males as well as CA1 Igf1r transcript levels in females." (PMID 41400881, 2025). "In addition to opiates, various studies evaluating IGF-1 have been conducted in alcohol dependent subjects but the authors did not observe any interaction between alcohol addiction and this peptide in blood or brain." (PMID 25734326, 2015).
Ataxia (10 papers, 2012 to 2025). Ataxia refers to impaired coordination of voluntary muscle movement. "Second to disease-specific mutations, dysregulation of the IGF-1 signalling pathway is a recurrent finding in mouse models for cerebellar ataxia." (PMID 26331037, 2014). "Notably, a correlation has been identified between the deficiency of the IGF-1 axis and elevated ataxia scores, coupled with severe neurodegeneration in this disorder." (PMID 39200370, 2024). "Several studies have shown an improvement in motor function after IGF-1 treatment in animal models of ataxia with different etiologies." (PMID 39859255, 2025). "In this context, neurotrophic molecules such as GDNF, and IGF-1 have been shown to promote Purkinje cell survival and to delay neurodegeneration and motor deficits in animal models of hereditary cerebellar ataxia." (PMID 41226418, 2025). "Studies in transgenic spinocerebellar ataxia type 3 mice have demonstrated that IGF-1 therapy is less effective than GH treatment, likely reflecting distinct regulatory mechanisms by which GH and IGF-1 confer neuroprotection." (PMID 41226706, 2025). "IGF-1 therapy seems to be beneficial for different brain diseases, including various types of cerebellar ataxia in animal models and human patients." (PMID 26331037, 2014). "IGF-1 has therapeutic effects for various types of cerebellar ataxias, exerting protective actions on mitochondrial function." (PMID 26331037, 2014). "IGF-1 has therapeutic effects in various types of cerebellar ataxia and exerts protective actions on mitochondrial function." (PMID 26331034, 2014). "Another form of ataxia in which IGF-1 has garnered attention, is ataxia telangiectasia (AT)." (PMID 39200370, 2024). "Treatment with IGF-1 has proven effective in neurotoxic and transgenic animal models of ataxia." (PMID 26331034, 2014). "Both ataxic animals and human patients with ataxia show altered serum IGF-1 levels." (PMID 26331037, 2014). "More specifically, several authors reported an amelioration of ataxia in PCD mice after IGF-1 treatment, resulting in improved motor coordination, but it is unclear whether these effects occurred by rescuing degenerating neurons or by modulating the function of surviving neurons." (PMID 39859255, 2025). "On clinical grounds, altered serum levels of IGF-1 and IGF-1 binding proteins (IGFBPs) have been reported in patients with late onset cerebellar ataxia (LOCA)." (PMID 26331034, 2014). "Abnormalities in the insulin/insulin-like growth factor 1 (IGF-1) system (IIS) signalling pathway were thought to play a role in the physiopathological processes of various neurodegenerative disorders, including spinocerebellar ataxias." (PMID 26331034, 2014).
Autoimmunity (10 papers, 2013 to 2025). The occurrence of an immune reaction against the organism's own cells or tissues. "The primary autoimmune effects can be inhibited by α-MSH, transforming growth factor-β1 (TGF-β1), and insulin-like growth factor-1 (IGF-1); meanwhile, secondary autoimmunity is inhibited by α-MSH, TGF-β1, and IL-10." (PMID 37511468, 2023). "We have recently shown that insufficient signaling through the IGF1/insulin receptor could initiate autoimmunity and contribute to RAab production." (PMID 36429105, 2022). "Growth factors acting on nutrition—leptin, insulin and insulin-like growth factor 1 (IGF-1) activate mTOR signaling in immune cells, and thus regulate immunometabolism, and when impaired contribute to inflammation and autoimmunity." (PMID 39599673, 2024).
cerebral infarction (10 papers, 2014 to 2024). An ischemic condition of the brain, producing a persistent focal neurological deficit in the area of distribution of the cerebral arteries. "Ischemia-induced cerebral infarction is more severe in older animals as compared to younger animals, and is associated with reduced availability of insulin-like growth factor (IGF)-1." (PMID 24618563, 2014). "Another group showed enhanced delivery efficiency of IGF1 via the intranasal route compared to the intravenous or intraperitoneal routes in a cerebral infarction model." (PMID 24959881, 2014). "In line with the findings in vitro, cyclocreatine administration could decrease the number of apoptotic neurons, and alleviate cerebral infarction and demyelination, as well as promoting the proportion of IGF1+ microglia, even in Trem2–/– mice." (PMID 38151703, 2024). "Insulin may be reducing the size of brain infarcts through the direct interaction of IGF-1 with brain tissue." (PMID 37025208, 2023). "overexpression of miR-320 by targeting IGF-1 could enhance brain infarction volume and edema volume in MCAO/R mice." (PMID 33768092, 2021). "The quantities of Iba-1+/IGF-1+ double-positive cells in the brain infarct area, both before and after MSC infusion, were very low, indicating that Iba-1+ cells may not be the major source of IGF-1 in the ischemic cortex." (PMID 32952570, 2020).
cyst (10 papers, 2013 to 2026). A sac-like closed membranous structure that may be empty or contain fluid or amorphous material. "Research has shown that Insulin-like Growth Factor 1 (IGF-1) can increase the growth of cyst-lining epithelial cells by promoting cell proliferation." (PMID 40801635, 2025). "There is evidence that NEB, low insulin and IGF-1, and altered metabolic hormones contribute to anovulation and cyst formation." (PMID 40725447, 2025). "Our data indicated that the average insulin and IGF-1 concentrations in the follicular fluids of follicular cyst follicles were significantly lower than in control follicles." (PMID 37958056, 2023). "Cyst fluid levels of IGF-1 and growth hormone correlated with cyst fluid levels of serum proteins, suggesting the importance of BBB dysfunction, whereas levels of erythropoietin and insulin did not correlate with serum protein levels in cyst fluid." (PMID 35659255, 2022). "The concentration of some hormones in cyst fluid was lower than (IGF-1, insulin) or similar to (growth hormone, testosterone, triiodothyronine) the serum concentration." (PMID 35659255, 2022). "In cyst fluid from 25 patients with cystic glioblastomas (nine women and 16 men), several hormones were present: IGF-1, insulin, erythropoietin, growth hormone, testosterone, estradiol, and free triiodothyronine." (PMID 35659255, 2022). "Their findings suggest that excessive mTORC1 activation—whether via nutrient overload, elevated BCAAs, or IGF-1 can exacerbate metabolic stress, promoting cyst growth and kidney dysfunction." (PMID 41235303, 2025). "In ADPKD, IGF-1 could be involved in cyst proliferation; in fact, some studies have found increased expression of IGF-1 in polycystic patients and animal models." (PMID 37299584, 2023). "Therefore, reduced insulin and IGF-1 levels may have an influence on the follicular responsiveness to LH stimulation and then result in ovulation failure and further cyst formation." (PMID 37958056, 2023). "In addition, insulin increases the bioavailability of insulin-like growth factor 1 (IGF-1) and both insulin and IGF-1 were reported to amplify the effects of LH on granulosa cells, leading to their premature differentiation which results in follicular growth arrest, anovulation and cyst formation." (PMID 32917200, 2020). "Adding forskolin or forskolin in combination with IGF-1 accelerated cyst expansion (data not shown)." (PMID 23383103, 2013).
glaucoma (10 papers, 2011 to 2025). Increased pressure in the eyeball due to obstruction of the outflow of aqueous humor. "Pigment epithelium derived factor (PEDF) reduces RGC loss in a mouse model of glaucoma and insulin-like growth factor-1 (IGF-1) also protects RGCs from different injuries." (PMID 32218163, 2020). "Together, these results support the contention that IGF-1 supplied by a targeted cell delivery system can effectively preserve the RGC layer in the setting of experimental glaucoma." (PMID 25923430, 2015). "We also evaluated the ability of hNPs expressing IGF-1 (fused to TD reporter protein) to confer trophic effects to host RGCs in the microbead model of mouse glaucoma." (PMID 25923430, 2015). "It has been suggested that GH and/or IGF-1 may directly or indirectly contribute to ocular dysfunction, which includes glaucoma and retinopathy." (PMID 35059575, 2021). "It is likely that the combination of IGF-1 and hNPs may be important for maintaining an anti-inflammatory and anti-angiogenic milieu in the setting of glaucoma." (PMID 25923430, 2015). "An interesting observation involves the effects of hNPs (including hNPTD) in absence of any IGF-1 on experimental glaucoma." (PMID 25923430, 2015).
Hypercholesterolemia (10 papers, 2015 to 2023). An increased concentration of cholesterol in the blood. "While the deficiency of GH aggravates hypercholesterolemia, the secretion and function of GH and IGF-1 might be negatively affected by high blood cholesterol level." (PMID 34220717, 2021). "However, this study has some limitations, including not performing other hormonal analysis such as GH, ACTH, hypercholesterolemia, and insulin-like growth factor 1, as it was not available in the local hospital." (PMID 36984475, 2023).
muscular atrophy (10 papers, 2019 to 2025). "Cisplatin-induced skeletal muscle atrophy is believed to be associated with not only the activation of muscle-specific ubiquitin ligases, but also reduced levels of IGF1, MyoD1, and myogenin." (PMID 37298128, 2023). "FoxO are related to muscular atrophy and caquexia with the use of certain chemotherapy treatments through the IGF1/AKT/FoxO pathways." (PMID 35897722, 2022). "Taken together, these findings suggest that irisin exerts a protective effect against muscle wasting by counteracting the effect of DEX on FoxO-mediated ubiquitin-proteasome overactivity and restoration of muscular atrophy through IGF-1-mediated signaling." (PMID 32219531, 2020). "Therefore, miR-29b targets PI3K and IGF-1 to promote various muscular atrophy in vivo and in vitro, such as in mouse models with cancer, aging, TNF-α, or denervation." (PMID 39404384, 2024). "Additionally, IGF-1 appears to decrease the expression of genes involved in protein degradation and consequently prevents muscular atrophy and improves feed efficiency." (PMID 35625092, 2022). "Additionally, while IGF-1 was able to counteract Ang II-regulated MAFbx expression via Akt-dependent FoxO1 repression, IGF-1 was unable to abolish MuRF1 up regulation, thus suggesting prevalence of TFEB in controlling MuRF1 expression in Ang II-dependent skeletal muscle atrophy." (PMID 32933049, 2020).
Turner syndrome (10 papers, 2012 to 2025). Turner syndrome is a chromosomal disorder associated with the complete or partial absence of an X chromosome. "Secondly, studies suggest that the GH-IGF axis is profoundly altered in Turner Syndrome, specific alterations include a reduction in bioactive IGF-1." (PMID 22472028, 2012). "Methylation of the IGF1 promoter P2 at two specific CG-sites was measured in the blood of children with GHD, SGA short stature and Turner syndrome treated with rhGH." (PMID 35769084, 2022). "This was a single tertiary center study analyzing clinical GH response and IGF-1 serum concentration changes in patients with GHD (n=40), SGA short stature (n=36), and Turner syndrome (n=16) treated with rhGH." (PMID 35769084, 2022). "The aim of this project was to analyze the clinical relevance of IGF1 promoter P2 methylation at DNA positions -137 and +97 in a cohort of children with GHD, Turner syndrome and SGA short stature treated with rhGH." (PMID 35769084, 2022). "The methylation of the P2 promotor of IGF1 at positions -137 and +97 could be determined in the blood of 40 children with GHD, 36 children with SGA short stature, and 16 children with Turner syndrome." (PMID 35769084, 2022). "However, in patients with relative IGF-1 resistance, such as the case with children born small for gestational age or girls with Turner syndrome, seem not to benefit from IGF-I titration within the normal range." (PMID 39906034, 2024). "In conclusion, we could not confirm that IGF1 P2 promoter methylation is an important epigenetic locus for GH responsiveness in children with GHD, SGA short stature and Turner syndrome." (PMID 35769084, 2022).
Uterine leiomyoma (10 papers, 2008 to 2026). The presence of a leiomyoma of the uterus. "According to research evidence, IGF-1 together with VEGF can be used as prognostic biomarkers to evaluate patients’ condition with uterine fibroids after UAE." (PMID 41514933, 2026). "IGF-1 can promote the proliferation of human uterine leiomyoma cells through the PI3K/AKT/mTOR pathway." (PMID 40428303, 2025). "The expression of various growth factors (EGF, IGF-1, TGF-β, and VEGF) was evaluated in uterine leiomyoma tissues." (PMID 36313223, 2022). "We observed multiple deregulated signaling pathways, including those for IGF-1, neuregulin, mTOR, TGFB1, CTNNB1, and TNF, in the mouse uterine leiomyomas." (PMID 33244099, 2020).